BRAF (B-Raf proto-oncogene, serine/threonine kinase)
Diseases named in the same sentence as BRAF in open-access papers (continued):
Sharing a sentence is not in itself a finding about the gene and the disease.
mucinous ovarian cancer (9 papers, 2006 to 2024). An invasive malignant neoplasm that arises from the ovary and is characterized by the presence of malignant epithelial cells that contain intracytoplasmic mucin and may resemble the epithelial cells of the endocervix or gastrointestinal tract. "The genetic mutation analysis found three mutations which were KRAS 27 cases (54%), PIK3CA 4 cases (8%) and BRAF 1 case (2%) The ovarian mucinous carcinoma patients with KRAS mutation in our study showed excellent prognosis." (PMID 31030485, 2019). "Mutations in KRAS and BRAF have been found to be common in low-grade serous and mucinous ovarian carcinomas." (PMID 17047655, 2006). "Molecular aberrations noted in mucinous ovarian cancer that suggest a match with current targeted therapies include amplification of ERBB2 (26.7%) and BRAF mutation (9%)." (PMID 32679669, 2020). "The suggestion is that blocking KRAS/BRAF signaling in mucinous ovarian carcinoma could potentially offer a more effective therapeutic approach." (PMID 38391958, 2024).
odontogenic tumors (9 papers, 2017 to 2025). "The identification of BRAF mutations in these tumors provides strong evidence for a shared oncogenic driver across the benign–malignant spectrum of mixed odontogenic neoplasms." (PMID 41364259, 2025). "Among the MAPK/ERK mutations reported in odontogenic tumors, the most prominent is BRAF p.V600E." (PMID 35048058, 2021). "Odontogenic tumors have been shown to harbor high frequencies of both BRAF and RAS mutations." (PMID 35048058, 2021). "Recent studies have provided robust evidence that the activation of the MAPK signaling pathway plays a significant role in the pathogenesis of this odontogenic tumor, with SMO and BRAF V600E mutations being the most observed." (PMID 38615253, 2024). "This suggests that analogous strategies could be advantageous for patients with other BRAF-positive odontogenic neoplasms." (PMID 41364259, 2025). "Besides being important for therapeutics, the elucidation of BRAF and RAS mutations in odontogenic tumors might be helpful to diagnosis and classification." (PMID 35048058, 2021). "To date, BRAF V600E mutations have been identified also in ameloblastic fibromas (2/2) and fibrodentinomas (1/1), as well as in ameloblastic carcinomas (3/8) and clear cell odontogenic carcinomas (1/1), but not in other odontogenic tumors." (PMID 28390134, 2017). "Further clinical trials addressing the use of BRAF, BRAF/MEK, and MEK inhibitors for odontogenic tumor treatment are necessary to clarify their effectiveness, the advantages and disadvantages, actual efficacy, and best treatment regimen for the patients." (PMID 35048058, 2021).
pancreatic ductal adenocarcinoma (9 papers, 2018 to 2024). An infiltrating adenocarcinoma that arises from the epithelial cells of the pancreas. "In addition, actionable mutations in genes including BRAF and DNA repair genes have been identified in around half of patients with pancreatic ductal adenocarcinoma using real-time whole-exome sequencing, with second-line targeted therapy showing early promise in selected patients." (PMID 37628794, 2023). "This siRNA suppressed the expression of BRAF, harboring the deletion without affecting wild-type BRAF expression in BxPC-3 pancreatic ductal adenocarcinoma cells in vitro and in vivo." (PMID 35804932, 2022).
pilomyxoid astrocytoma (9 papers, 2014 to 2025). An astrocytic tumor of uncertain relation to pilocytic astrocytoma. "All KIAA1549::BRAF fusion-positive LGGs were confirmed to have a PA (N = 158), pilomyxoid astrocytoma (PMA, N = 9), mixed pilocytic/pilomyxoid astrocytoma (N = 2), or fibrillary astrocytoma (N = 3) diagnosis." (PMID 39847453, 2025).
plexiform neurofibroma (9 papers, 2021 to 2025). An elongated and multinodular neurofibroma, formed when the tumor involves either multiple trunks of a plexus or multiple fascicles of a large nerve, such as the sciatic. "Three cohorts of patients were treated with the MEK inhibitor trametinib: cohort 1 (BRAF fusion–positive LGG), cohort 2 (NF1-related optic pathway glioma), and cohort 3 (NF1-related plexiform neurofibroma)." (PMID 37399010, 2023).
prostate tumors (9 papers, 2008 to 2024). "This study, together with recently reported BRAF mutations in human prostate tumors, demonstrates the pathogenetic relevance of MAP kinase activation in prostate tumorigenesis." (PMID 19079609, 2008).
serous borderline ovarian tumor (9 papers, 2009 to 2025). "Ovarian serous borderline tumor (SBT) is a known precursor of low-grade serous carcinoma, and it has been reported that about 50% of SBTs are BRAF-mutated and that these tumors have a better prognosis." (PMID 39001384, 2024).
spitzoid melanoma (9 papers, 2015 to 2025). "Their results show that a small subgroup of Spitz nevi with atypia harbored BRAF mutations; therefore, assessing BRAF mutations cannot differentiate all Spitz nevi from Spitzoid melanomas." (PMID 31531096, 2019). "Spitzoid melanomas with BRAF mutations are also associated with worse clinical outcomes." (PMID 40507250, 2025). "Spitzoid melanomas (e.g., BRAF mutated) were not included in our study." (PMID 40227833, 2025). "Finally, the third group is Spitzoid melanoma, where NRAS and BRAF mutations are absent and the lesions often have a less aggressive clinical course." (PMID 33996584, 2021).
acromegaly (8 papers, 2014 to 2025). Acromegaly is an acquired disorder related to excessive production of growth hormone (GH) and characterized by progressive somatic disfigurement (mainly involving the face and extremities) and systemic manifestations. "The mutation rate of BRAF V600E in the PTCs of patients with acromegaly varied in previous studies." (PMID 29593792, 2018). "Further studies with a larger number of patients and long-term follow-up are needed to understand the role of BRAF in thyroid abnormalities in acromegaly." (PMID 29593792, 2018). "PTC in acromegaly shares some of the molecular events occurring in other PTC patients, such as somatic BRAF mutations." (PMID 25019383, 2014). "Unexpectedly, PTCs unassociated with acromegaly revealed a high AHR protein expression as well, which was particularly evident in the BRAF-mutated cases." (PMID 25019383, 2014). "AIP protein expression was similar in neoplastic and normal cells, while AHR protein was expressed more in PTCs carrying BRAF mutations than in normal tissue, irrespective of acromegaly status." (PMID 25019383, 2014). "With this in mind, we looked at whether the main genetic drivers of DTC (BRAF and RAS mutations) were important in acromegaly-related DTC too, and we assessed the expression in DTC of the key molecular drivers of acromegaly (AIP and AHR)." (PMID 25019383, 2014). "Moreover, AIP expression was similar between neoplastic and normal tissue, while the aryl-hydrocarbon receptor (AHR) was expressed more in PTCs carrying BRAF mutations than in normal tissue, irrespective of acromegaly status." (PMID 32333269, 2020). "Our results are not in accordance with previous data, which suggested that BRAF mutation may not play a dominant role in development of DTC in patients with acromegaly." (PMID 32333269, 2020). "This AHR overexpression in PTC (particularly in BRAF-mutated cases) irrespective of a patient's acromegaly status could reflect a close relationship between AHR and BRAF." (PMID 25019383, 2014). "However, it is not known whether the BRAF mutation is associated with PTC in patients with acromegaly." (PMID 25329702, 2014). "Conversely, a recent study concluded that the BRAF V600E mutation was present in 14.3% of the patients diagnosed with DTC and acromegaly, while none of them harbored the NRAS codon 61 mutation." (PMID 37374352, 2023). "In these studies only one (9.1%) or two (14.3%) patients with concomitant PTC had the BRAF mutation, which in both studies was more frequently present in PTC patients without acromegaly." (PMID 32333269, 2020). "In our sample, the most common oncotype in acromegaly-related DTC was PTC (10 out of 12 cases) with a high frequency (70%) of BRAF V600E mutations, whereas none of our cases harbored RAS mutations." (PMID 25019383, 2014). "However, only one patient (9.1%) with acromegalic PTC had the BRAF mutation, which was a significantly lower frequency than that in PTC patients without acromegaly." (PMID 25329702, 2014). "Although the limited number of PTCs in the present series prevents us from drawing any final conclusions on the prevalence of BRAF mutations in PTCs in patients with versus without acromegaly, BRAF was the main genetic driver of follicular cell transformation in our cases of acromegaly-related PTC." (PMID 25019383, 2014).
autoimmune disease (8 papers, 2011 to 2024). A disorder resulting from loss of function or tissue destruction of an organ or multiple organs, arising from humoral or cellular immune responses of the individual to their own tissue constituents. "This is of special importance in patients with pre-existing autoimmune diseases, as reflected by our case of MS disease reactivation under treatment with BRAF/MEK inhibitors." (PMID 38074649, 2023). "Further evaluation of BRAF-specific antibodies in autoimmune diseases and other inflammatory diseases would strengthen the conclusions of this study." (PMID 22174938, 2011). "The objective of this study was to determine antibody responses to the catalytic domain of BRAF in RA and other autoimmune diseases." (PMID 22174938, 2011). "Patient characteristics that may favor RT over systemic therapies for adjuvant treatment include lack of a targetable BRAF mutation, high risk of toxicity to systemic therapies including those with a history of autoimmune disease, and/or patient preference." (PMID 36816935, 2023). "Thus, the involvement of autoantibodies to BRAF in other autoimmune diseases is still unclear." (PMID 22174938, 2011). "Extensive studies on antibody responses to BRAF in other autoimmune diseases such as pSS and SLE might contribute to a comprehensive understanding of its role in autoimmune disorders." (PMID 22174938, 2011).
bladder urothelial carcinoma (8 papers, 2011 to 2025). "In this study, we used commercially available AI histology software to predict BRAF mutation in whole slide images (WSI) of bladder urothelial carcinomas (UC) stained with haematoxylin and eosin (HE), based on a training (n = 81) and a validation set (n = 96)." (PMID 37570213, 2023). "The present study aimed to test AI histology to predict the presence of the BRAF V595E mutation in canine urinary bladder urothelial carcinomas." (PMID 37570213, 2023). "Involvement of BRAF mutations in the development of transitional cell carcinoma of the bladder has been reported to be rather infrequent." (PMID 21483670, 2011). "Comparatively, in vitro studies of canine urinary bladder transitional cell carcinoma harboring orthologous BRAFV600E mutations (e.g., canine V595E) have shown response to the BRAF kinase inhibitor Vemurafenib, while tumor cells with wild-type BRAF were unresponsive to the drug." (PMID 29385676, 2018).
Cognitive impairment (8 papers, 2017 to 2025). Abnormal cognition is characterized by deficits in thinking, reasoning, or remembering. "Collectively, these data indicate that BRAF KE–associated cognitive impairment arises due to dysregulation of astrocytic ERK signaling and a subsequent disruption of Ca2+ regulation." (PMID 39964758, 2025). "Together, our results demonstrate that cognitive impairments linked to the BRAF KE mutation are mediated by astrocytic dysfunction — more specifically, an aberrant increase in Ca2+ signaling in mature astrocytes." (PMID 39964758, 2025). "Neurocognitive evaluation evidenced a mild-to-severe cognitive impairment in all of the participants and autistic spectrum features in one case (BRAF mutation)." (PMID 37510243, 2023). "Neurocognitive phenotypes tend to be more variable but ‘downstream’ mutations in BRAF, MEK1, or MEK2 generally result in more severe cognitive deficits than ‘upstream’ mutations." (PMID 31017896, 2019).
corticotroph adenomas (8 papers, 2018 to 2023). "A small number of non-USP8-driven corticotropinomas are due to somatic hotspot variants in USP48 or BRAF; the latter is a well-known mutational hotspot in cancer." (PMID 38067388, 2023). "We next examined the prevalence of USP48 and BRAF mutations in additional corticotroph adenomas with wild-type USP8 by targeted sequencing." (PMID 30093687, 2018). "The results supported the potential efficacy of vemurafenib in the treatment of corticotroph adenomas with the BRAF V600E mutation." (PMID 30093687, 2018). "In this study the authors report USP48 and BRAF are frequently mutated in USP8 wild-type corticotroph adenomas, and cause Cushing’s disease mainly through promoting the promoter activity of POMC." (PMID 30093687, 2018). "Moreover, compared to wild-type cells, primary cultured human corticotroph adenoma cells with BRAF mutations displayed greater reduction of ACTH secretion in response to the BRAF inhibitor vemurafenib." (PMID 36672445, 2023). "Inhibition of BRAF may be a promising therapeutic strategy for the treatment of patients with BRAF-mutated corticotroph adenomas." (PMID 30093687, 2018). "Recently, USP48 and BRAF have been reported as additional target genes, with somatic variants of BRAF gene in 16% of patients and of USP48 gene in 23% of USP8-negative corticotropinomas." (PMID 31877737, 2019). "We assumed that mutations in BRAF and USP48 should be involved in the pathogenesis of corticotroph adenomas." (PMID 30093687, 2018). "In our study, an elevated kinase activity of BRAF V600E compared to wild-type BRAF was observed in corticotroph adenomas just like in other types of tumors, leading to activation of MAPK pathway and transactivation of POMC, which is the precursor of ACTH." (PMID 30093687, 2018). "When we ectopically expressed BRAF V600E in a murine cell line of corticotroph adenoma (AtT-20), we observed elevated phosphorylation of Erk1/2, an indicator of MAPK activation, compared to cells with wild-type BRAF expression." (PMID 30093687, 2018). "In summary, our study identified frequent BRAF and USP48 mutations in corticotroph adenomas carrying wild-type USP8 and indicated that these mutations cause Cushing’s disease mainly by activating POMC gene transcription and increasing plasma ACTH levels." (PMID 30093687, 2018). "Our findings suggest an immediately operable drug target for corticotroph adenomas carrying BRAF V600E." (PMID 30093687, 2018). "We next sought to evaluate the effect of the BRAF inhibitor vemurafenib on ACTH secretion in primary human corticotroph adenomas." (PMID 30093687, 2018). "The mutational status of BRAF, USP8, and USP48 in corticotroph adenomas may be used in the future to characterize the molecular subtypes and guide targeted molecular therapy." (PMID 30093687, 2018). "Therefore, similar to USP8, BRAF and USP48 mutations appear to be unique genetic signatures of corticotroph adenomas." (PMID 30093687, 2018). "Somatic BRAF V600E mutation has been reported in several tumors; in 2018, such a mutation was detected in 16.5% of a case series of USP8-WT corticotrope adenomas; this alteration was not mutually exclusive with USP48 mutations." (PMID 35743266, 2022).
diabetes (8 papers, 2015 to 2025). "Reporting a diabetes diagnosis was more strongly associated with BRAF‐mutated tumors in both the proximal colon and rectum indicating that tumor location does not explain this result." (PMID 35383926, 2022). "Although this is in line with our own results, where individuals reporting diabetes had a higher incidence of BRAF‐mutated tumors compared to other molecular markers, later studies have been unable to replicate the findings." (PMID 35383926, 2022). "We first used the LASSO Logistic regression method to exclude four variables (BMI, nodular composition, BRAF V600E mutation and diabetes) that would affect the fitting." (PMID 36506061, 2022). "They found that diabetes appears to increase the risk of tumors with BRAF mutations, which generally have poorer outcomes." (PMID 35383926, 2022). "In the case only analysis, BRAF‐mutation was differentially associated with diabetes (Pdifference = .03)." (PMID 35383926, 2022). "Also, some confounding factors, such as patient comorbidities (in our study most common comorbidities were included in statistical analysis such as HTA and diabetes mellitus) and relevant molecular markers (e.g., BRAF, RAS, TERT, etc.), could have had an impact on the results." (PMID 39767178, 2024).
dysembryoplastic neuroepithelial tumor (8 papers, 2015 to 2023). A benign glial-neuronal neoplasm. "Dysembryoplastic neuroepithelial tumors (DNT) share V600E mutation in the BRAF gene with other low grade neuroepithelial tumors (LGNTs)." (PMID 27791984, 2017). "Less common tumor entities that harbor an oncogenic BRAF signaling are the epilepsy-associated dysembryoplastic neuroepithelial tumor (DNT) and the rare desmoplastic infantile gliomas (DIA/DIG)." (PMID 31181803, 2019). "Dysembryoplastic neuroepithelial tumors (DNETs) harbored alterations in MAPK/PI3K pathway genes, as was previously reported, including FGFR1 (21%, 4/19), PDGFRA (10%, 2/19), and BRAF (5%, 1/19)." (PMID 37492101, 2023).
histiocytic sarcoma (8 papers, 2015 to 2025). An aggressive malignant neoplasm with a poor response to therapy, usually presenting as stage III/IV disease. "Description of our successful clinical experience highlights that investigation for BRAF mutations in histiocytic sarcoma is potentially advantageous." (PMID 40057687, 2025). "Mutation in exon 15 of BRAF V600 (V600E, V600K and V600R) was detected, and the diagnosis was revised to histiocytic sarcoma." (PMID 40057687, 2025). "According to recent studies, certain histiocytic sarcomas include BRAF alterations, including V600E and non-V600E variants." (PMID 36721560, 2022). "On a molecular basis, alterations affecting the RAS/RAF/MAPK signaling cascade - such as KRAS, NRAS, BRAF, and others - are commonly reported in histiocytic sarcoma." (PMID 40901224, 2025). "Other BRAF mutations in LCH and histiocytic sarcomas include BRAF V600D, BRAF F595L, and BRAF V600insDLAT in LCH and histiocytic sarcoma." (PMID 38963520, 2024). "The BRAF mutant V600E has been found in both histiocytic sarcoma and hairy cell leukemia in one patient with concurrent diseases, further indicating a common genetic ancestor." (PMID 36721560, 2022).